APOE (apolipoprotein E)
Diseases named in the same sentence as APOE in open-access papers (continued):
Sharing a sentence is not in itself a finding about the gene and the disease.
Alzheimer disease (continued). "In particular, the missense variant rs429358 in the APOE gene is linked to 24 different traits, including those previously identified conditions such as macular degeneration, abdominal aortic aneurysm, dementia, Alzheimer’s disease, and HDL levels." (PMID 37425708, 2023). "The APOE ε4 allele has been linked with elevated tau and amyloid pathology and atrophy in the medial temporal lobe regions (the brain structures implicated in olfactory processing and early Alzheimer’s disease), even in cognitively normal individuals." (PMID 37630831, 2023). "APOE-ε4 has been widely shown to be a significant risk factor for Alzheimer’s disease and dementia." (PMID 36891556, 2023). "Furthermore, APOE ε4 is a well-known risk factor for Alzheimer’s disease and is also linked with better kidney function." (PMID 37605228, 2023). "Importantly, APOE genotype impacts well established associations among Alzheimer’s disease (AD), type 2 diabetes (T2D), and cardiovascular disease (CVD)." (PMID 36837905, 2023). "This genetic association study analyzes data from 4 Alzheimer disease and cognitive aging cohorts to investigate whether sex and race modify associations of APOE ε4 and ε2 with cognition." (PMID 37459083, 2023). "Apolipoprotein E ε4 allele (APOE-ε4) is the main genetic risk factor for late-onset Alzheimer’s disease (AD) and may impact cognitive function also via other neuropathological lesions." (PMID 38115150, 2023). "Apolipoprotein E4 (ApoE4) is the most important genetic risk factor for Alzheimer’s disease (AD)." (PMID 37290814, 2023). "ApoE is also implicated in Aβ clearance and is considered an Alzheimer’s disease (AD) risk factor." (PMID 37513702, 2023). "A severe genetic risk factor for Alzheimer’s disease (AD) is the ε4 allele of the APOE (APOE4) gene that encodes for apolipoprotein E4, and its effect on vascular function is widely unknown." (PMID 36645735, 2023). "Alzheimer’s disease (AD), for example, is oligogenic, meaning it is primarily influenced by a small number of genetic variants—including apolipoprotein E (APOE), a gene that codes for proteins that bind and transport low-density lipids and contribute to cholesterol clearance from the bloodstream." (PMID 38048316, 2023). "The APOE 2/3/4 polymorphism is the greatest genetic risk factor for Alzheimer’s disease (AD)." (PMID 37666928, 2023). "Notably, the joint predictor for Alzheimer’s disease was significantly associated with carrying one or two APOE e4 alleles, which is a well-known genetic risk factor for Alzheimer’s disease but is not included in the polygenic risk score for this analysis." (PMID 35710731, 2022). "The current results suggest that the quantification of mIns levels could provide a preferential astrocytic marker reflecting some of the impact of APOE ε4 allele on the pathophysiology of Alzheimer’s disease." (PMID 35702728, 2022). "A polymorphism of the ApoE gene ε 4 is considered a genetic risk factor for Alzheimer's disease." (PMID 35983158, 2022). "We speculate that the correlation between APOE gene expression and brain metabolism, especially among regions most affected by Alzheimer’s disease, could be another indicator of risk for the disease." (PMID 36092303, 2022). "We identified single nucleotide polymorphisms in genes associated with Alzheimer's disease including a novel apolipoprotein E (Apoe) gene variant that correlated with an increase in amyloid plaques in brain and modified the in silico predicted degu APOE protein structure and functionality." (PMID 35860672, 2022). "Moreover, 14.33% of the subjects had a CC or CT genotype of rs429358 (APOE) with the dominant C genotype being the risk allele for coronary heart disease and Alzheimer's disease." (PMID 36050800, 2022).
Alzheimer disease (continued). "The major haplotype, H1, has been genetically associated with increased risk for multiple neurodegenerative disorders, including APOE ɛ4-negative Alzheimer’s disease (AD), corticobasal degeneration (CBD), progressive supranuclear palsy (PSP) and Parkinson’s disease (PD)." (PMID 35841044, 2022). "Apolipoprotein E (APOE), a gene identified as one of the strongest genetic factors contributing to the risk determinant of developing late-onset Alzheimer’s disease (AD), may also contribute to the risk of cancer." (PMID 37304007, 2022). "[10.1016/j.nbd.2004.01.015] (accessed on 26 July 2022) Amyloid beta (Aβ), known to cause Alzheimer’s disease, is hypothesized to accumulate in the brain as plaques and is regulated by receptors for ApoE." (PMID 35955522, 2022). "Supporting this, in Alzheimer's Disease (AD), APOE e4 is the preeminent genetic risk factor." (PMID 35911887, 2022). "The first community contains variants rs199499 and rs7207400, that are reported in the GWAS catalogue as associated to trait Alzheimer's disease in APOE ε4- carriers and that present a low LD in the general population (r2 = 0.18) and moderate LD (r2 = 0.52) in the European population." (PMID 35061909, 2022). "Therefore, future longitudinal studies are needed to examine the extent to which sex and APOE ɛ4 impact the association of cardiovascular risk and accumulation of tau over the course of Alzheimer’s disease." (PMID 35233525, 2022). "In addition to proteins known to play a pathophysiological role in Alzheimer’s disease such as APOE, numerous other proteins were associated with the polygenic score and replicated in the MESA cohort." (PMID 36048760, 2022). "Given that APOE is primarily expressed in astrocytes, these cells might be an important link between the APOE ε4 allele and the development of Alzheimer’s disease pathology." (PMID 35702728, 2022). "Apolipoprotein E4 (ApoE4) is thought to increase the risk of developing Alzheimer’s disease." (PMID 35454088, 2022). "IL-33 expression was shown to be lower in the brains of Alzheimer's disease patients when compared to controls, and additional genetic investigation revealed three variants within the IL-33 gene, indicating a protective haplotype linked with Alzheimer's disease risk in non-APOE e4 carriers patients." (PMID 35224555, 2022). "Among them, the ancestral ApoE ε4/ε4, generally considered deleterious, is a significant risk factor for Alzheimer’s disease and other human pathologies, including type 2 diabetes and cardiovascular disease, which are known risk factors for worst outcomes of COVID-19." (PMID 35793369, 2022). "Such difference could also have had an impact on the sensitivity to the effect of APOE on the association between mIns and Alzheimer’s disease pathology." (PMID 35702728, 2022). "Subtypes of apoE have been implicated in Alzheimer’s disease, cardiovascular disease, and T2DM." (PMID 35937834, 2022). "Genetic variants within the APOE locus may modulate Alzheimer’s disease (AD) risk independently or in conjunction with APOE*2/3/4 genotypes." (PMID 35120553, 2022). "This is the case, for instance, of the ApoE ε4 allele, which confers an increased risk for Alzheimer’s disease but is far from being considered a Mendelian mutation, since multiple genetic variants, as well as non-genetic determinants, jointly modify the risk of sporadic Alzheimer’s disease." (PMID 35167423, 2022). "Moreover, carriership of the ε4 allele of APOE, which represents the greatest genetic risk for Alzheimer’s disease, can be easily assessed by inexpensive, simple blood screening." (PMID 35831715, 2022). "APOE gene is strongly associated with the onset of Alzheimer’s disease." (PMID 35691989, 2022).
Alzheimer disease (continued). "Amyloid plaques caused by an amyloid precursor protein (APP) gene mutation, neurofibrillary tangles (NFT) caused by tau protein gene mutation, missense mutations of the presenilin-1 (PS-1) gene, and the apolipoprotein E typeE4 (ApoE4) allele are closely associated with Alzheimer’s disease." (PMID 35624994, 2022). "However, in a related study, researchers found the exact opposite effect: presence of the APOE-4 allele significantly lowered the CLU level in the frontal lobe region of people with Alzheimer’s disease." (PMID 36291661, 2022). "Moreover, the links between APOE gene polymorphisms, Alzheimer’s disease, and cardiovascular disease have been extensively studied." (PMID 35885971, 2022). "APOE is a strong genetic risk factor for Alzheimer’s disease and age-related cognitive decline." (PMID 35160273, 2022). "As a “Mendelian disease” caused by a “single gene” with dominant inherited disease of incomplete penetrance, it also provides a disease model to explore pathogenic roles of APOE in some common diseases, such as Alzheimer's disease, type III hyperlipoproteinemia (HLP), and coronary artery disease." (PMID 35602473, 2022). "Whether future clinical trials would benefit from incorporating consideration of APOE Ɛ4 genotype, or other genetic markers associated with Alzheimer’s disease, into the study design remains to be determined." (PMID 35633431, 2022). "Collectively, the screening, clinical management and ideally prevention of ARIA-H during Aβ immunotherapy trials are potentially relevant to limiting clinical deterioration, especially in Alzheimer’s disease patients with co-occurring CAA or APOE ε4 carriers who are at increased risk." (PMID 35224489, 2022). "In humans APOE ε2 may provide some protection against Alzheimer's disease, but people with this allele can still develop the disease." (PMID 35860672, 2022). "In this regard, apoE in the brain contributes to the pathogenesis of Aβ accumulation and this process is accelerated in ε4 carriers to increase the risk of amyloid-associated Alzheimer’s disease." (PMID 36077289, 2022). "This study of the effects of APOE alleles ɛ2 and ɛ4 using structural brain scans from UK Biobank participants shows that the protective effect of the APOE ɛ2 allele on Alzheimer’s disease risk is sex-specific and linked to distinct hippocampus-default network co-variation regimes." (PMID 36512526, 2022). "One explanation could be that the absolute Alzheimer’s disease risk of APOE ε4 carriers is so pronounced that the additional presence or absence of a weaker risk factor, such as inflammation, may not have much impact." (PMID 36085081, 2022). "In addition, evidence suggests that carrying the apolipoprotein E (APOE) epsilon 4 allele increases the likelihood of developing Alzheimer's disease." (PMID 35634389, 2022). "The APOE ε2 and ε4 variants have previously been associated with a decreased (ε2) or increased (ε4) risk for several age-related diseases, such as CVDs and Alzheimer’s disease (AD), which could explain the APOE effect on longevity." (PMID 35628444, 2022). "The correlation of disentangled SPARE-AD was non-inferior to amyloid- and tau-related measurements and to the number of APOE ε4 alleles but was lower to Alzheimer’s disease-related psychometric test scores, suggesting the contribution of advanced brain ageing to the latter." (PMID 35611306, 2022). "Meta-analysis of the associations of the APOE ε4 allele with Alzheimer’s disease (AD) biomarkers." (PMID 36399096, 2022). "Besides, the ApoE ε4 allele is considered the strongest genetic risk factor for late-onset Alzheimer’s disease (AD) in humans, but the underlying mechanism of how ApoE influences the development of AD is still under investigation." (PMID 35886936, 2022). "The APOE locus is a well-established genetic risk factor for Alzheimer’s disease (AD)." (PMID 36337698, 2022).
Alzheimer disease (continued). "The TOMM40/APOE locus has been reported to be associated with longevity in multiple studies among diverse populations and the locus contributes to Alzheimer's disease, age‐related macular degeneration, cardiovascular disease, cognitive decline, immunity, and lipid metabolism/dyslipidemia." (PMID 33657282, 2021). "In addition to its strong association with Alzheimer’s disease, APOE is known to be involved in fatty acid metabolism." (PMID 32393786, 2021). "Indeed, translocase of outer mitochondrial membrane 40 (TOMM40), which lies in linkage disequilibrium with the APOE gene, has previously been reported to be associated with Alzheimer’s disease." (PMID 34943074, 2021). "The presence of specific human apolipoprotein E (ApoE) isoforms is the best-known risk factor for developing late-onset Alzheimer’s disease (LOAD), although the mechanism underlying its role is unknown." (PMID 34795427, 2021). "APOE-ε4 allele is the strongest genetic risk for late-onset form of Alzheimer’s disease (LOAD)." (PMID 34155245, 2021). "•The Apolipoprotein-E (APOE) ε2 allele is known to be protective against Alzheimer’s disease." (PMID 32961217, 2021). "In addition to ageing, APOE ε4 is genetically the strongest risk factor for Alzheimer’s disease and is highly expressed in astrocytes." (PMID 33559106, 2021). "In addition, increased levels of adiponectin have been reported in CSF from patients diagnosed with multiple sclerosis or Alzheimer's disease, and APOE is associated with a genetic predisposition to late-onset Alzheimer's disease (Burke and Roses, 1991-1992)." (PMID 34870700, 2021). "Both Alzheimer’s disease and cerebral amyloid angiopathy are strongly associated with the ε4 allele encoding the apoE4 isoform of apoE, and the clearance process of apoE4-Aβ complexes from brain tissue through capillary endothelial cells is less efficient than that of apoE3-Aβ and apoE2-Aβ." (PMID 33925284, 2021). "Genetic variants of APOE are unambiguously associated with human longevity and Alzheimer's disease." (PMID 33336875, 2021). "Earlier meta-analysis suggested sex differences in the APOE genotype-Alzheimer’s disease (AD) association, but several experimental and neurobiological studies indicated that the impact of APOE4 on neurodegeneration was more tangible among women compared to men." (PMID 34193248, 2021). "There is a significant association between the ε4 allele of APOE and Alzheimer's disease." (PMID 33763108, 2021). "Elderly peoplewith ApoE4, known to pose an increased risk to develop Alzheimer’s disease, are known toundergo a more severe course of COVID-19 than people who are non-carriers, and ApoE e4e4homozygotes are more likely to be COVID-positive compared to e3e3 homozygotes." (PMID 34222864, 2021). "The ɛ4 allelic variant of APOE could increase the risk for cognitive impairment and Alzheimer’s disease in diabetic patients." (PMID 35154608, 2021). "Abnormal ApoE methylation and low levels of ApoE-particles in the brain correlate with an increased risk of Alzheimer disease (AD), which may have overlapping mechanisms with ASD." (PMID 34803605, 2021). "Using NEBULA in Alzheimer’s disease cohort data sets, we found that the cell-level expression of APOE correlated with that of other genetic risk factors (including CLU, CST3, TREM2, C1q, and ITM2B) in a cell-type-specific pattern and an isoform-dependent manner in microglia." (PMID 34040149, 2021). "Hippocampal volume decline might be a more prominent Alzheimer’s disease risk-related pathology in APOE e4 homozygous women than men." (PMID 33615215, 2021). "In chronic peripheral inflammation, endothelia in brain capillary beds could play a role for the apolipoprotein E4 (ApoE4)‐mediated risk for Alzheimer's disease (AD) risk." (PMID 34687487, 2021). "Interestingly, the association of Alzheimer’s disease biomarker concentration and mnemonic discrimination deficits remained even after accounting for APOE status." (PMID 33987536, 2021).
Alzheimer disease (continued). "However, of interest, the 52i ALS line contains the APOE-ε4 allele (rs429358) (C130R), which is associated with an increased risk of developing Alzheimer’s disease." (PMID 34746695, 2021). "We have shown that genetically predicted PVR expression is correlated with the number of APOE e4 alleles, and that the TWAS association with Alzheimer’s disease risk may therefore be due to APOE effects." (PMID 33959712, 2021). "ApoE genotype has been observed to be implicated as a risk factor in several neurological disorders such as Alzheimer’s Disease, Creutzfeldt-Jacob disease, Wilson’s disease, Multiple Sclerosis, cerebral amyloid angiopathy, Parkinson’s Disease and Lewy Body Dementia." (PMID 34200812, 2021). "In addition to Alzheimer’s disease, ApoE has been implicated in other diseases such as parkinsonism and HIV-related dementia, further highlighting SELENOP1-ApoER2 interaction as an area of interest in neurodegeneration research." (PMID 33927588, 2021). "We also included four additional phenotypes for which GWAS results became available after our study was underway, as well as Alzheimer’s disease, motivated by the association we found between APOE and macronutrient intakes, and nine phenotypes from the psychiatric domain." (PMID 32393786, 2021). "APOE ε4 is the most significant genetic risk factor for developing late-onset Alzheimer’s disease, and several studies investigated whether there was an interaction of APOE ε4 carriage with rosiglitazone or pioglitazone effects on cognition." (PMID 34220427, 2021). "Presubiculum and subiculum volume across ageing and APOE status may therefore be useful markers of future cognitive decline and may explain the relationships observed with both ageing and Alzheimer’s disease risk across studies." (PMID 33615215, 2021). "Apolipoprotein E4 (apoE4) is a major genetic risk factor of Alzheimer’s disease." (PMID 33676568, 2021). "As a proof of concept, we show first the results from an analysis of common and rare variants within a 200 kb region near the apolipoprotein E (APOE) gene for Alzheimer’s Disease (AD), using data on 3,894 individuals from the Alzheimer’s Disease Sequencing Project (ADSP)." (PMID 34035245, 2021). "In parallel to the adaptive process, amyloid-β deposition was more pronounced in peri-menopausal and post-menopausal women carrying apolipoprotein E-4 (APOE-4) genotype, the major genetic risk factor for late-onset Alzheimer’s disease, relative to genotype-matched males." (PMID 34108509, 2021). "Apolipoprotein E (APOE) 4 is the strongest genetic risk factor for Alzheimer’s disease (AD)." (PMID 34537055, 2021). "By far the greatest risk factor of Alzheimer’s disease, but also implicated in some forms of Parkinson’s disease, is the gene Apolipoprotein E (APOE), which is involved in the transport of cholesterol and other fatty acids or compounds." (PMID 35002678, 2021). "APOE and Trem2 are major genetic risk factors for Alzheimer’s disease (AD), but how they affect microglia response to Aβ remains unclear." (PMID 34099706, 2021). "Consistently, the overall m6A level was elevated in the cortex and the hippocampus of APP/PS1 (Alzheimer’s disease) mice compared to C57BL/6 control mice, and FTO was found to interact with APOE, which is associated with Alzheimer’s disease risk in a prospective cohort study." (PMID 33611339, 2021). "Importantly, ApoER2 is also a receptor for ApoE, for which the e4 polymorphism is the most prominent genetic risk factor for Alzheimer’s disease." (PMID 33927588, 2021). "The APOE ε4 allele of the major ligand ApoE for ApoER2, increases risk of Alzheimer's disease." (PMID 34277682, 2021). "Similarly, the rs429358 C allele (APOE e4), a risk factor for Alzheimer's disease, was associated with decreased PhenoAgeAccel but increased BioAgeAccel although the association with BioAgeAccel didn't reach genome‐wide significance (p = 1.3 × 10−7)." (PMID 34038024, 2021).